IL1A (interleukin 1 alpha)
Diseases named in the same sentence as IL1A in open-access papers (continued):
Sharing a sentence is not in itself a finding about the gene and the disease.
tumor (continued). "The reason for this could be that the tumor inhibitor miR101 is disturbed in tumor-derived exosomes under hypoxic stress, leading to the upregulation of cyclin-dependent kinase 8 (CDK8) in macrophages and the stimulation of IL1A and IL6 secretion in macrophages." (PMID 36071472, 2022). "Although IL-1α is not specific for megakaryocyte rupture, and a rise could also be due to inflammation, as can arise secondary to infection, cell stress/tissue injury or ischemia or due to tumor development, the absence of an increase in IL-1α makes megakaryocyte rupture very unlikely." (PMID 33661336, 2021). "This liposome could significantly increase the cytokine rations of IL-12/IL-4, IL12/IL-1α, IL-12/IL-1β, IFN-γ/IL-6, IFN-γ/IL-1α, and IFN-γ/IL-1β by 1.18–3.14-fold, (P < 0.05), thus favoring the balance of Th1 and Th2 cells to stimulate antitumor effects in the tumor microenvironment." (PMID 31915707, 2019). "Additionally spaghetti plots of individual mice in each of the treatment groups showed complete regression in 9/10 mice in the CTX + IL-1α-NP treatment group compared to no tumor regression in the CTX + IL-1α-NP + anti-CD4 and CTX + IL-1α-NP + anti-CD8 treatment groups." (PMID 30890189, 2019). "The poor clinical outcome associated with the BRD4+/high group in the absence of T-bet+ TILs suggests that BRD4 may promote tumor progression through upregulation of chronic inflammatory pathways marked by the production of proinflammatory cytokines such as IL-1α, IL-1β, and IL-6." (PMID 30029633, 2018). "If IL-1α expression in tumor cells is elevated in the absence of IL-15-dependent cell-mediated immunity, and it contributes to tumor cell death in the context of a competent immune system, we asked if IL-1α could be used as a therapeutic target." (PMID 24416335, 2014). "Interestingly, IL-1α abundance in the skin surrounding the tumor was independent of IL-15." (PMID 24416335, 2014). "We have previously identified IL-1α to be the main tool used by the tumor cells to activate CAFs to produce several inflammatory factors (e.g., IL-6, CCL20, CXCL8, COX-2, and VEGF-A), and this could be one mechanism the tumor cells use to escape elimination by the immune system." (PMID 22190968, 2011). "One often reported cytokine subfamily upstream of TNFα is IL-1α and IL-1β; of which, IL-1α, but not IL-1β, is produced during MMTV-PyMT tumor pathology." (PMID 37134077, 2023). "Hypoxia has no influences in regulating IL1A or IL6 expression in macrophages, but instead dramatically promotes their expression in the co-culture with tumor cells." (PMID 36071472, 2022). "IL-1α-loaded polyanhydride nanoparticles did not affect the anti-tumor efficacy of cetuximab and their combination with cetuximab induced a T cell-dependent anti-tumor immune response and may represent a novel immunotherapeutic strategy for EGFR-positive HNSCCs." (PMID 36338731, 2022). "Some M1 markers (IL1A, IL1B, CD86), M2 markers (CCL18, MRC1/CD206, CSF1R), and TAM markers (HLA-DR, IL1RN, CD163, ITGAM, SIGLEC1/CD169) were highly expressed on both tumor and non-tumor macrophages." (PMID 33918618, 2021). "Knockdown of PTBP1 attenuates secretion of pro‐inflammatory factors including IL‐6, IL‐8 and IL‐1α without affecting NRasG12V‐driven OIS, thereby impeding tumour growth in mouse livers and in squamous cell carcinoma xenografts." (PMID 32981205, 2021). "To in depth elucidate the effect of IL-1α on tumor cell migration we used PC077, a primary PDAC cell line that is IL-1α negative." (PMID 23951028, 2013). "To examine whether the combination of IL-1α and LIF in the absence of G-CSF is relevant to human disease, we reexamined human tumor RNA-sequencing datasets from TCGA and other sources." (PMID 37134077, 2023).
tumor (continued). "Since inflammation in the tumor microenvironment includes a marked increase in IL-1α production, we examined the effects of dexamethasone and OLT1177 on 1205Lu cells either with or without 10 ng/mL of recombinant IL-1α." (PMID 36672229, 2023). "Serum IL‐1α was significantly reduced in the stressed mice, and chronic repetitive activation of VTATH projections in the mPFC led to a significantly higher IL‐1α serum level than control mice and even higher than that of tumor‐bearing mice without stressors." (PMID 33112032, 2021). "The importance of non-secreted IL-1α, and thus of cell-cell contacts, for VEGF-A and VEGF-C expression was also demonstrated, because the levels of these factors were much higher in direct, rather than indirect, co-cultures of macrophages and tumor cells." (PMID 24924428, 2014).
infection (582 papers, 2007 to 2026). The state of being infected such as from the introduction of a foreign agent such as serum, vaccine, antigenic substance or organism. "In the transcriptomic analysis of rabbits at 6 dpi with MPXV, pathways related to pathogenic infection and inflammatory response were enriched, and inflammatory genes such as IL1A, IL1B, and CXCL8 were significantly upregulated." (PMID 41157589, 2025). "This increased disease severity occurs in the innate phase of the infection and is associated with increased recruitment of innate immune cells into the lungs orchestrated by IL-1α and TNF-α." (PMID 39127259, 2024). "IL-1RN is an antagonist of IL-1 that inhibits the activities of IL-1α and IL-1β and regulates several immunological and inflammatory reactions linked to IL-1, especially during the acute stage of infection and inflammation." (PMID 39354641, 2024). "Anti-Duo treated mice were protected from weight loss on day 1–2 post infection, confirming that IL-1α and TNF-α are the main drivers of early weight loss in this model." (PMID 39127259, 2024). "At day 3 post-infection, young and aged neutrophils expressed similar levels of Il1b, but young neutrophils expressed higher levels of Il1a; the chemokines Ccl3, Cxcl3, and Cxcl1; and Cd274 (encodes PD-L1)." (PMID 37852965, 2023). "Association of TLRs and MyD88-mediated pathway during infection by Leishmania was first studied in 2002, reporting decreased IL-1α expression in MyD88−/− mice upon infection by L. major." (PMID 35531875, 2022). "IL-1α is an important immunoregulatory cytokine that depending on the magnitude of stress or damage caused by the infection can initiate an inflammatory response or reparative fibrosis." (PMID 33868272, 2021). "Specifically, drivers of coagulation, including the gene coding for tissue factor F3, as well as pro-inflammatory cytokines IL23A and IL1A were specifically associated with WT infection." (PMID 33529199, 2021). "The induction of IL-8, IL-6, CXCL2 and IL-1α upon infection was significantly suppressed by overexpressing the mutated PUF60." (PMID 32538777, 2020). "During the infection caused by different microbial agents, very similar profiles of the human innate immune response are observed including secretion of IL-1α, IL-8, and IFN-α, and suppression of superoxide dismutase, IL-1Ra and IL-17A release." (PMID 32751625, 2020). "IL-1R1−/− mice, deficient for cell signaling in response to both IL-1α and IL-1β, are more susceptible to most infections, including those caused by GAS, GBS, and SPN." (PMID 26500655, 2015). "The level of mRNA encoding 4 interleukins (Il10, Il11, Il1rn, Il1a) was increased and 1 interleukin (Il18) decreased in vaginal tissue collected at 35 days post-infection." (PMID 26779389, 2015). "After both 4 and 8 hours of infection, many of the up-regulated genes were those that encode pro-inflammatory cytokines (IL-1α, IL-1β, IL-6 and TNF-α) and chemokines (CCR7 and IL-8), all of which have been implicated in RA and CVD pathogenesis." (PMID 24874661, 2014). "IL-1α and IL-1β double deficient mice exhibited strongly increased lung weights, an indicator of lung inflammation, 5 weeks post-infection, as did IL-1R1 deficient mice and TNF KO mice which succumbed at 4 weeks." (PMID 25400917, 2013). "IL-1α levels were slightly increased in IL-1β deficient mice, and conversely, IL-1β levels were slightly increased in IL-1α deficient mice during the first 2 months of infection." (PMID 25400917, 2013). "Mice deficient only for IL-1α or IL-1β had less pronounced pulmonary inflammation on day 35 post-infection." (PMID 25400917, 2013). "The levels of IL-17A were also reduced in mice deficient for both IL-1α and/or IL-1β or IL-1R1 at 5 weeks post-infection and in IL-1α or IL-1β single deficient mice at 8 weeks post-infection." (PMID 25400917, 2013).
infection (continued). "In previous reports, deficiency in IL-1α or IL-1β led to either early death after M. tuberculosis infection or survival up to 3–6 months at lower dose infection." (PMID 25400917, 2013). "Previous studies have shown that DCs from L. major susceptible mice produced low quantities of IL-1α and IFNγ in response to LPS and this was thought to be responsible for different outcomes after infection by the parasite." (PMID 21857913, 2011). "Although, IL-1α transcripts were similarly elevated in iDCs at 1 h post-infection with either wild type or lipase deficient C. parapsilosis, the increase was significantly greater with the lipase deficient yeast cells (p < 0.05)." (PMID 21619700, 2011). "Having seen that IL-1α was necessary for weight loss following infection, we wanted to determine whether IL-1α in the lungs was sufficient to cause weight loss." (PMID 38382577, 2024). "IL-1α levels, most commonly associated with epithelial cell or macrophage necrosis in the lungs, were elevated at least by day 3 and through day 7 of infection in A/J lungs indicating high necrotic damage prior to and during the development of an antiviral response." (PMID 36685578, 2022). "IL-1α and IL-1β are key players in the innate immune system; IL-1α is implicated in the initiation/maintenance of the immune response to infection; and IL-1β is produced by activated macrophages, T lymphocytes, and NK cells and is essential for the initiation of the immune response." (PMID 35431938, 2022). "IL-1α–deficient mice are susceptible to infection with low-dose aerosolized Mtb." (PMID 34236051, 2021). "The interleukin 1 (IL-1) cytokine family (IL-1α, IL-1β, IL-18, IL-33, IL-36α, IL-36β, and IL-36γ) acts as DAMPs and stimulates sterile inflammation caused by necrosis and increases the inflammation with infection-related tissue damage." (PMID 32184728, 2020). "The most important observation is that the minor allele (T) of IL1A genes could influence the infections due to T. b. gambiense in HAT foci of southern Cameroon." (PMID 30908482, 2019). "IL-1A and -B encode proinflammatory cytokines involved in host defense against infection." (PMID 28423679, 2017). "The negative impact that such a response could have is considerable, as recent evidence suggests that genetic variants of IL-1α and IL-1β may exert a substantial impact on the susceptibility of H1N1pdm09 infection." (PMID 25831059, 2015). "Deficiency in either IL-1α or IL-1β allowed some bacterial growth restriction on day 35 post-infection, and there was a limited increase in bacterial load at 2–3 months post-infection." (PMID 25400917, 2013). "At 2–3 months post-infection lung pathology in mice deficient for IL-1α or for IL-1β progressed with reduced free alveolar space, increased inflammatory cell infiltration, acid-fast bacilli abundance and oedema, as compared to wild-type mice, but still little necrosis." (PMID 25400917, 2013). "TNF deficient mice rapidly lost weight and succumbed by 6 weeks of infection with highly inflammed lung, spleen and liver, while IL-1R1 and IL-1α plus IL-1β deficient mice survived systemic M. bovis BCG infection with lung, spleen and liver weight similar to wild-type mice at 6 and 11 weeks." (PMID 25400917, 2013). "However, IL-1α or IL-1β deficient mice survived to a more chronic infection and lung inflammation was gradually increased in these animals 2 or 3 months post-infection." (PMID 25400917, 2013). "The interleukin-1 (IL-1) cytokine family, including IL-1α, IL-1β, IL-18, IL-33, IL-36α, IL-36β, and IL-36γ, acts as DAMPs and stimulates sterile inflammation due to tissue necrosis, while also enhancing inflammation associated with tissue damage from infection." (PMID 41214565, 2025).
infection (continued). "The animal model of chronic airway infection differs significantly from those used in prior studies of IL-1α and IL-1β during A. fumigatus infection in which mice were infected with either a high dose of conidia, or were immunosuppressed to render them susceptible to infection." (PMID 34322116, 2021). "Notably, proinflammatory cytokine genes Il-1α, Il-6, Il-7, and Il-17, as well as anti-inflammatory genes Il-6 and Il-13, were downregulated after an infection caused by the 267/47 strain compared to those after infection with the H37Rv strain." (PMID 34442871, 2021). "With the CMH test, the minor allele T of rs1800794 in IL1A which is located in the promoter region was significantly associated (unadjusted P = 0.0012, X2 = 30.01, adjusted P = 0.009) with an increased risk to be infected by T. b. gambiense and develop this infection." (PMID 30908482, 2019). "However, IL-17 (including increased expressions of Il17a, Il1a and Il22) and granulocyte-associated (L10 and L11) responses were most pronounced during B. pseudomallei infection, with this infection also exhibiting increased IFN gene signatures (L5 and L7) in contrast to the C. albicans infection." (PMID 31253760, 2019). "With CMH test, the minor allele T of rs1800794 in IL1A remains significantly (unadjusted P = 0.0005, X2 = 11.99, adjusted P = 0.004) associated with an increased risk of getting T. b. gambiense and develop this infection in the Bantu major ethno-linguistic group." (PMID 30908482, 2019). "On the other hand, in vivo over-expression of IL-1α in mice led to a faster clearance of VACV upon skin scarification infection, which may help to explain why S2V caused a lesion so small and was so rapidly cleared in our experiments of intradermal infection in BALB/c mice." (PMID 27973399, 2016). "Infection with all the multi-deletion mutants except sap2∆/∆ hgc1∆/∆ (GM-CSF, IL-1α, and IL-1β) and sap2∆/∆ ece1∆/∆ (IL-1α) led to a significant reduction in cytokine secretion." (PMID 41294335, 2026). "This study demonstrates the differential expression of immunological (IFN-γ, IP-10 and IL-1α) and physiological (TAS) biomarkers in goats reacting to TB diagnostic tests and suggest their potential as biomarkers of cTB infection." (PMID 41800411, 2026). "Among the identified genes, both DMBT1 and IL-1α genes exert an active role in mounting an effective immune response during infection including M. bovis." (PMID 39858163, 2025). "Cluster 0 myeloid cells emerged as a prominent population post‐PA infection, characterized by the expression of Il12a, Il1a, Ccl4, and Csf3 genes, indicative of a pro‐inflammatory M1‐like phenotype." (PMID 40087815, 2025). "Proinflammatory cytokines IL-6 and IL-1α were significantly upregulated post-infection, while IL-8 and CXCR1 were differentially expressed, indicating their involvement in neutrophil recruitment and immune modulation." (PMID 40453956, 2025). "Exceptions to this were IL1α, which favored the apical compartment, and IL-6, which changed from being expressed in both compartments to basolateral during late infection (6 dpi)." (PMID 41157615, 2025). "IL‐1a is released into the extracellular space upon cellular damage or programmed cell death, and it can alert neighbouring cells to impending damage or infection." (PMID 40342218, 2025). "Although transcription of IL-1α, IL-1β, IL-6, and IL-15 genes was substantially upregulated, overall cytokine responses to infection with VR-2332 were insignificant." (PMID 40302751, 2025). "Pre-incubation with either HCMV variant for 24 h or 72 h before infection with A. fumigatus significantly and time-dependently suppressed gene expression and secretion of key cytokines such as CXCL8, VEGFA, IL-1α, IL-1β, IFN-γ, and TNF-α." (PMID 40980889, 2025).